INS (insulin)
Diseases named in the same sentence as INS in open-access papers (continued):
Sharing a sentence is not in itself a finding about the gene and the disease.
Hyperinsulinemia (continued). "Strikingly, insulin-induced translocation of KCC1 and PIT2 to the PM was impaired in adipocytes rendered insulin resistant by chronic hyperinsulinemia, accompanied by increased perinuclear retention under basal conditions." (PMID 41690593, 2026). "Elevated leptin levels result in declined responsiveness of pancreatic β cells, inability to suppress insulin secretion, and hyperinsulinemia." (PMID 41549047, 2026). "High protein meals invoke postprandial hyperinsulinemia which can depress insulin sensitivity if repeated frequently." (PMID 41602572, 2026). "Elevated C-peptide, a marker of compensatory hyperinsulinemia and reduced adiponectin, an insulin-sensitizing adipokine, contribute to the metabolic dysregulation observed in PCOS." (PMID 41827122, 2026). "In contrast, the Co-culture+PA group exhibited a sustained increase in insulin secretion (1 h: 22.3 ± 0.9 μg/L; 12 h: 26.6 ± 0.4 μg/L; 24 h: 27.1 ± 0.5 μg/L), indicative of persistent β-cell activation and a potential state of hyperinsulinemia." (PMID 41328336, 2026). "Fetal hyperinsulinism leads to stimulation of glycogen accumulation, increased lipid synthesis, and disproportionate growth of insulin‐sensitive tissues, including liver tissue." (PMID 40920364, 2026). "Additional studies in congenital hyperinsulinism have utilized iPSC-derived SC-islets to model disease-specific hallmarks such as excess insulin secretion and increased beta cell proliferation." (PMID 42318217, 2026). "Apart from its anti-inflammatory properties, butyrate also inhibits pancreatic insulin secretion, thereby lowering hyperinsulinemia and improving insulin sensitivity." (PMID 40699823, 2025). "Serum insulin levels are mainly regulated by pancreatic β-cells, and hyperinsulinemia is a sign of pancreatic dysfunction or overfunctioning." (PMID 41156477, 2025). "Experimentally inducing hyperinsulinemia through insulin infusion also reduces whole-body glucose utilization in humans." (PMID 40013621, 2025). "In conclusion, these results suggest that the measurement of hepatic GU during euglycemic hyperinsulinemia gives useful insight about insulin's ability to promote hepatic GU in physiologic context." (PMID 40391305, 2025). "This elevates blood insulin levels, potentially leading to beta-cell damage due to hyperinsulinemia." (PMID 40881124, 2025). "Early stages feature hyperinsulinemia with reduced insulin signaling in muscle, liver, and adipose tissue (e.g., impaired GLUT4 translocation, glycogen synthesis)." (PMID 41280935, 2025). "This study explored targeted dietary interventions to manage hyperinsulinemia and to enhance glucose uptake in insulin-sensitive organs under high-carbohydrate diet." (PMID 41004024, 2025). "Experimental models confirm that sustained hyperinsulinemia alone can induce endocrinopathic laminitis, a mechanism consistent with the elevated insulin levels observed in horses with high BCS and SFT in this study." (PMID 41302145, 2025). "Hyperinsulinemia can result from both reduced insulin uptake due to decreased insulin receptor levels and attenuation of insulin signaling pathway by modification the intermediate signaling molecules like the insulin receptor substrates." (PMID 40643485, 2025). "The potential cardiovascular benefits of insulin sparing and reducing peripheral hyperinsulinemia warrant further study." (PMID 41285865, 2025). "IDE plays a vital role in degrading both insulin and Aβ, and in cases of hyperinsulinemia common in T2DM, the enzyme can become overwhelmed." (PMID 40724942, 2025). "This persistent hyperinsulinemia, however, is accompanied by reduced pancreatic insulin expression due to pancreatic β-cell dysfunction." (PMID 40286055, 2025). "In hyperinsulinemia, the increased insulin secretion of pancreatic β-cells can recruit further partners for the facilitation of glucose uptake and the maintenance of normal glucose level." (PMID 41514592, 2025).
Hyperinsulinemia (continued). "We found that Mig-6 levels are reduced in adipose tissue from obese individuals and ob/ob mice with hyperinsulinemia, despite stress and insulin being strong inducers of Mig-6 expression." (PMID 39937764, 2025). "Thus, in this concept genetic susceptibility, consumption of the “modern” Western diet, and environment, may all cause and contribute to (primary) hyperinsulinemia by enhancing pancreatic insulin secretion, decreasing insulin pulses, and/or reducing hepatic insulin clearance." (PMID 41009753, 2025). "Since insulin is a dominant fetal growth hormone, fetal hyperinsulinemia accelerates fetal growth and, therefore, macrosomia is more likely to occur." (PMID 40589878, 2025). "Insulin dysregulation (ID) is a hallmark feature of EMS, encompassing fasting hyperinsulinemia, post-prandial hyperinsulinemia and peripheral tissue insulin resistance." (PMID 41408266, 2025). "By enhancing insulin sensitivity via activation of insulin signaling pathways, they indirectly regulate androgen biosynthesis, which is often stimulated by hyperinsulinemia in PCOS." (PMID 40427455, 2025). "Chronic sugar consumption induces hyperinsulinemia and disrupts insulin receptor signalling, resulting in reduced cellular responsiveness to insulin." (PMID 40216734, 2025). "For example, pancreatic cancer animal models suggest a prominence of hyperinsulinemia and significant impairment of insulin secretion; therefore, both insulin sensitivity and β-cell function are impaired." (PMID 40984953, 2025). "Carbohydrate intake can promote insulin secretion, and hyperinsulinemia can stimulate myofibrillar protein synthesis." (PMID 40801034, 2025). "Fasting plasma insulin levels were evaluated in all groups to assess the presence of compensatory hyperinsulinemia." (PMID 40563843, 2025). "Physiological IR and hyperinsulinemia occur during systemic infection, trauma, starvation, adolescence, and pregnancy, and limit glucose uptake in insulin-dependent tissues, such as muscle and adipose tissue." (PMID 40565766, 2025). "Estrogen deficiency has a profound impact on insulin-stimulated glucose uptake in skeletal muscle; muscle-specific ERα knockout mice demonstrate a 45% reduction in insulin-stimulated glucose disposal during a hyperinsulinemia euglycemic clamp." (PMID 40522859, 2025). "As evident from the response, the proposed FRNN-FO algorithm demonstrates superior performance in effectively modeling the chaotic behavior of hyperinsulinemia within the insulin-glucose regulatory system compared to other identification techniques." (PMID 41345203, 2025). "Blood biochemicals and metabolites, hormones, and antioxidants in Arabian mares with hyperinsulinemia (insulin >20 mIU), overweight (BW > 400 kg), and control (BW < 400 kg), and normal insulin (insulin <20 mIU)." (PMID 40901060, 2025). "In order to overcome this peripheral hyperinsulinemia, other routes of administration of insulin are being developed, such as the oral route." (PMID 40427546, 2025). "Insulin clearance, primarily performed by the liver (50–80%), is essential for managing glucose metabolism and preventing hyperinsulinemia in insulin‐resistant individuals." (PMID 40365648, 2025). "The absorption and utilization of nutrients (e.g., glucose, lipids) were affected by the hyperinsulinemia and insulin; to obtain more energy, the nutrients were expended more, and there was no nutrition to store." (PMID 41376068, 2025). "This reduces circulating insulin levels and thereby indirectly lessens the stimulatory effect of hyperinsulinemia on ovarian androgen production." (PMID 41586011, 2025). "Hyperinsulinemia, secondary to IR, is a ‘silent killer’ that leads to chronically elevated levels of circulating insulin and C-peptide." (PMID 41463398, 2025).
Hyperinsulinemia (continued). "Severe insulin resistance syndrome is defined as “a severely diminished response to insulin’s biological effects, and is characterized by substantial hyperinsulinemia, and impaired glucose response to endogenous and exogenous insulin”." (PMID 40565151, 2025). "When analyzing fasting insulin (FI), it was observed that syrup intake promoted a significant hyperinsulinemia denoting IR, which was completely abolished by Met treatment, as expected." (PMID 41155548, 2025). "A recognized pathophysiological mechanism in this context is systemic hyperinsulinemia, resulting from exogenous insulin administration, which bypasses hepatic first-pass metabolism." (PMID 40429855, 2025). "Free fatty acid overload is rooted in caloric surplus, obesity, and decreased insulin sensitivity of adipocytes, leading to enhanced fat mobilization and persistent hyperinsulinemia." (PMID 40958906, 2025). "Using in vivo, ex vivo, and in vitro models, we now show that the mechanism of sustained hyperinsulinemia in the setting of FATP2 inhibition or deletion was α cell–mediated GLP-1 secretion with paracrine stimulation of β cell insulin secretion." (PMID 40956612, 2025). "This pathological state is characterized by a reduced sensitivity of peripheral tissues to insulin, concurrently accompanied by compensatory hyperinsulinemia." (PMID 41301787, 2025). "Hyperinsulinemia—resulting from compensatory pancreatic insulin secretion—fosters a pro-inflammatory, pro-oxidant, and pro-growth environment, conducive to tumor progression and myocardial remodeling." (PMID 40564016, 2025). "Insulin sensitivity was evaluated via the hyperinsulinemia–euglycemic clamp both during and immediately after exposure." (PMID 41462642, 2025). "Hyperinsulinemia is characterized by excessive insulin secretion from β-cells in response to prolonged high glucose levels." (PMID 41345203, 2025). "SCFAs increase insulin sensitivity by promoting GLP-1 and PYY, which cause hyperinsulinemia, a well-known stimulator of androgen synthesis in ovarian theca cells." (PMID 40234859, 2025). "Chronic elevation in peripheral insulin (peripheral hyperinsulinemia) levels impacts central insulin availability and function." (PMID 40943177, 2025). "Insulin-resistant individuals often develop compensatory hyperinsulinemia, which, over time, leads to pancreatic β-cell dysfunction and overt diabetes." (PMID 40281870, 2025). "Insulin enhances glycogen stores in the liver, and patients with chronic hyperinsulinemia are expected to show a greater than 25 mg/dL rise in blood glucose following glucagon injection." (PMID 40083398, 2025). "First, a self-reinforcing calcium cycle is established: calcium-triggered β-cell dysfunction and peripheral insulin resistance (as detailed in Section 3) lead to hyperinsulinemia and hyperglycemia, which promote hyperuricemia (as outlined in Section 2)." (PMID 41301787, 2025). "Among natural molecules with insulin-sensitizing properties, inositols have proven effective in normalizing IR and hyperinsulinemia in dysmetabolic patients, mainly in overweight and obese women, or in women with polycystic ovary syndrome (PCOS)." (PMID 40235665, 2025). "In HFD-fed rats, due to the infusion of somatostatin inhibiting their hyperinsulinemia, insulin levels during the clamp steady-state were low and close to the baseline levels of control rats." (PMID 39562740, 2025). "Metformin enhances insulin sensitivity by lowering blood glucose levels and decreasing hyperinsulinemia, which indirectly affects AMH levels." (PMID 40281834, 2025). "It is commonly accompanied by compensatory hyperinsulinemia, where the pancreas increases insulin production to maintain normal glucose levels." (PMID 40564201, 2025). "A central feature is hyperinsulinemia: T2DM patients often exhibit elevated insulin and IGF-1 levels, particularly in the early stages of the disease, which serves as a growth signal for epithelial cells." (PMID 41374093, 2025).
Hyperinsulinemia (continued). "Median BMI was higher in patients with hyperinsulinemia than in those with normal insulin levels (29.4, range 22.0-46.1 vs. 25.8, range 16.9-32.0 kg/m2; P < 0.001)." (PMID 41488138, 2025). "Initially, these cells compensate by producing more insulin, resulting in hyperinsulinemia; however, over time, they lose function, leading to persistent hyperglycemia." (PMID 40565464, 2025). "This study aims to evaluate the potential of targeted dietary supplements to manage hyperinsulinemia and to enhance glucose uptake in insulin-sensitive organs under high-carbohydrate diet." (PMID 41004024, 2025). "When converted into Inositol triphosphate, insulin’s action is facilitated thus reducing the chance of compensatory hyperinsulinemia." (PMID 40566517, 2025). "IR is characterized by diminished sensitivity and responsiveness of insulin target tissues, resulting in reduced glucose uptake and utilization, which triggers compensatory hyperinsulinemia and glucose metabolism disorders." (PMID 41469741, 2025). "Conversely, omega-3 fatty acids, found in fatty fish and flaxseeds, exhibit anti-inflammatory and insulin-sensitizing effects, counteracting the pro-cancer effects of hyperinsulinemia and IGF-1 signaling." (PMID 40428567, 2025). "Nevertheless, insulin levels remain higher than those in db/+ mice, indicating persistent hyperinsulinemia." (PMID 40286055, 2025). "This state leads to sustained hyperinsulinemia, which promotes carcinogenesis through its effects on the insulin/IGF system." (PMID 41002547, 2025). "Increased ROS production impairs insulin signaling, leading to hyperinsulinemia, which stimulates androgen overproduction, disrupting follicular development and ovulation." (PMID 40427455, 2025). "At the same time, fiber slows down carbohydrate absorption, reduces postprandial blood glucose spikes, and indirectly inhibits insulin secretion, thereby reducing fat synthesis triggered by hyperinsulinemia." (PMID 40958906, 2025). "Peripheral insulin administration, mostly using multiple injections, and hyperinsulinemia are major reasons for conservation of calories, lipid accumulation, and weight gain." (PMID 39998445, 2025). "Impaired ER expression/activation or low estrogen levels upregulate compensatory insulin secretion, leading to hyperinsulinemia as an attempt to restore estrogen signaling, even if this effort is not successful." (PMID 41514592, 2025). "In cancer, hyperinsulinemia supports tumor growth by activating insulin and IGF-1 receptors, promoting mitogenic signaling via PI3K/Akt and MAPK pathways." (PMID 40564016, 2025). "In response to elevated BER and in hyperinsulinemia conditions, the extracellular matrix can remodel itself and accumulate collagen deposition, increasing physical barriers to glucose, insulin and fatty acid transport and decreasing vascular delivery." (PMID 40549708, 2025). "When IR develops, compensatory hyperinsulinemia occurs due to the increased secretion of insulin from the pancreatic β-cell to achieve normoglycemia, which leads to an inadequate or vicious cycle of IR ↔ hyperinsulinemia." (PMID 40943177, 2025). "A primary treatment target is therefore the increase in insulin sensitivity to keep insulin requirements and inappropriate hyperinsulinemia as low as possible." (PMID 39998445, 2025). "Insulin dysregulation (ID) is a consistent feature of equine metabolic syndrome, often presenting with hyperinsulinemia as a common occurrence." (PMID 39113254, 2025). "Myoinositol is arguably one of the most prescribed supplements for women with PCOS, due to its proven ability to restore ovulatory function and improve insulin sensitivity, thereby reducing hyperinsulinemia and promoting hormonal balance." (PMID 41041518, 2025). "To compensate, pancreatic β-cells increase insulin secretion, marking the onset of hyperinsulinemia." (PMID 41150735, 2025).
Hyperinsulinemia (continued). "The primary explanation for the link between IR and vascular endothelial dysfunction is impaired insulin action due to receptor resistance and its consequent hyperinsulinemia." (PMID 40406487, 2025). "Traditional studies have demonstrated that hyperinsulinemia disrupts the balance of the insulin‐growth hormone‐insulin‐like growth factor axis, shifting the insulin‐to‐growth hormone ratio toward insulin and away from growth hormone." (PMID 40550558, 2025). "Overfeeding, especially with excess carbohydrates, can rapidly decrease hepatic insulin clearance by about 15% leading to systemic hyperinsulinemia." (PMID 39998445, 2025). "It is characterized by decreased insulin sensitivity (IS), also termed increased insulin resistance (IR), initial beta cell compensation with hyperinsulinemia, and eventual beta cell dysfunction and progression to glucose intolerance and hyperglycemia." (PMID 41614817, 2025). "It has been proved that under the conditions of hyperinsulinemia, sensitivity to insulin and glucose utilization is decreased only in peripheral tissues, for example, muscular tissue, whereas there is no decrease in insulin levels in the ovaries." (PMID 40281834, 2025). "CAT activity (p = 0.004) and NO (p = 0.0001) levels were maximum in mares with normal insulin-light BW and were minimum in hyperinsulinemia-light mares." (PMID 40901060, 2025). "The ob/ob mice exhibit impaired glucose tolerance and insulin sensitivity reflecting a more pre-diabetic stage, whereas db/db mice are insulin resistant and display hyperinsulinemia as well as hyperleptinaemia." (PMID 40427173, 2025). "Hyperinsulinemia is a subtle signal of the genome indicating successful restoration of estrogen signaling, but it occurs at the expense of excessive insulin synthesis." (PMID 41514592, 2025). "Insulin directly influences follicular development, and chronic hyperinsulinemia disturbs folliculogenesis by accelerating early antral growth but impairing terminal maturation, resulting in follicular arrest and anovulation." (PMID 41155686, 2025). "Hyperinsulinemia is one of the first indications of IR, and dysfunction of insulin clearance is a sign of metabolic health abnormality." (PMID 40259008, 2025). "SREBP-1c is an essential mediator of the lipogenic response to insulin and carbohydrate intake, and its upregulation is often observed in metabolic disorders characterized by hyperinsulinemia, such as obesity and type 2 diabetes." (PMID 40004991, 2025). "Compensatory hyperinsulinemia in insulin-resistant states further activates MAPK pathways, amplifying ET-1 release and upregulating adhesion molecules (e.g., VCAM-1, E-selectin), promoting monocyte adhesion and atherosclerosis." (PMID 40564010, 2025). "In the state of pre-prediabetes, the levels of insulin rise meet the physiological needs of insulin resulting in chronic hyperinsulinemia, with increased blood sugar leading to pancreatic beta cell failure and T2D development." (PMID 39859066, 2025). "Mice transfected with extra copies of the human insulin gene to induce hyperinsulinemia became insulin resistant and showed evidence of insulin receptor downregulation in their livers (Marbán & Roth 1996)." (PMID 40013621, 2025). "In the prediabetic state, insulin levels increase to fulfill physiological demands, leading to chronic hyperinsulinemia and subsequent β cell dysfunction, which ultimately culminates in the development of type 2 diabetes." (PMID 40283443, 2025). "In IDE knockout mouse models, insulin degradation in liver and brain tissues is reduced by approximately 58–72%, resulting in chronic hyperinsulinemia and significantly elevated Aβ levels in the brain." (PMID 40724942, 2025). "In contrast to the presence of obese mares with normal insulin levels and others with hyperinsulinemia, insulin sensitivity was found to decrease with increasing BCS and body fat percentage in horses." (PMID 40901060, 2025).